DGAT2 (diacylglycerol O-acyltransferase 2)
Diseases named in the same sentence as DGAT2 in open-access papers (continued):
Sharing a sentence is not in itself a finding about the gene and the disease.
Hepatic steatosis (continued). "Fatty acid uptake and TAG synthesis were involved in VPA-induced hepatic steatosis by increasing the expression of CD36 and DGAT2." (PMID 31379584, 2019). "Caloric substitution with fiber-rich apple pomace attenuated hepatic steatosis due to elevated hepatic MUFA content, higher circulating bile acids, and upregulated hepatic DGAT2 gene expression induced by a Western (high fat/high sugar) diet." (PMID 30513881, 2018). "Similar protective effects have been observed with liver-specific overexpression of DGAT2, which induced hepatic steatosis without activating inflammatory markers such as p-JNK and p-NFkB, as seen in high-fat diet-induced steatosis." (PMID 39456242, 2024). "In addition, we examined the enrichment of repressive histone marks H3K9me2 and H3K27me2 on the promoter of DGAT2 in KDM7A-overexpressing AML12 cells and assessed the development of hepatic steatosis in vivo in KDM7A-overexpressing mice." (PMID 34681759, 2021). "Hepatic deletion of DGAT2 reduced hepatic steatosis but showed no increase in inflammation and fibrosis in mice." (PMID 34681759, 2021). "BMP inhibition also resulted in reduced hepatic steatosis without altering glucose tolerance, which is consistent with previous studies which showed that manipulation of Dgat2 impacted hepatic steatosis without affecting glucose tolerance." (PMID 32561790, 2020). "Expression of DGAT2 gene is involved in TG synthesis; meanwhile, it has been reported that PPARγ might be involved in HFD-induced liver steatosis." (PMID 31019978, 2019). "Besides, it is worth noting here that although VPA treatment alone induced Dgat2 expression, lipid accumulation only increased when cells were cotreated with OLA, indicating the importance of fatty acid uptake in VPA-induced hepatic steatosis." (PMID 27034954, 2016). "The absence of OPN reversed HFD-induced fatty liver, as shown by the reduction of lipogenic gene expression of Srebf1, Mogat1 and Dgat2 and TG accumulation in the liver." (PMID 24871103, 2014). "Because the expression of CD36, DGAT2, and PLIN2 in liver is previously known to be regulated by PPARγ, a crucial nuclear transcription factor controlling cellular glucose and lipid metabolism, we also investigated whether PPARγ is involved in VPA-induced hepatic steatosis." (PMID 27034954, 2016).
Obesity (37 papers, 2007 to 2025). Accumulation of substantial excess body fat. "We also found that TRF-mediated inhibition of Dgat2 prevents lipid metabolism dysfunction in the periphery and prevents age and obesity-associated dysfunction." (PMID 39596576, 2024). "Mice with DGAT1 deficiency are lean and resistant to diet-induced obesity, while DGAT2 deficiency results in reduction of the majority of fat in the whole body." (PMID 38500157, 2024). "In triacylglycerol synthesis pathway, DGAT1 is not essential but seems to be better drug target for care of obesity because mice deficient in DGAT2 die shortly after birth." (PMID 22676350, 2012). "Furthermore, we observed a positive correlation between the reduction of glucose and proteins associated with alleviating obesity and type 2 diabetes, such as Insig2, Dgat2 and Rbp4." (PMID 38188177, 2024). "Sex-dependent obesity-associated metabolic complications has been correlated to sex-dependent modulation of two major genes involved in adipogenesis (Sfrp4) and in TG synthesis (Dgat2)." (PMID 34997206, 2022). "We conclude that the reduced susceptibility to diet‐induced obesity and dyslipidemia in p50−/− mice results from an increase in metabolic rate, which is associated with elevated skeletal muscle oxidative metabolism and decreased DGAT2 expression." (PMID 30251338, 2018). "Genetic variations leading to a gain of function of DGAT2 may thus be associated with obesity, whereas variations entailing a reduced function could be relevant in underweight." (PMID 17477860, 2007). "Hence, assuming that a gain of function might well lead to obesity, it is reasonable to consider the Valin to Alanin substitution in DGAT2 as a potential cause for the patient's remarkably increased BMI." (PMID 17477860, 2007). "DGAT2 is an important enzyme involved in the synthesis of TG, and the buildup of TG in adipose tissue is a key factor in the development of obesity." (PMID 41157845, 2025). "In obesity-related gastric cancer, DGAT2 promotes lipid droplet formation in adipocytes and helps cancer cells resist anoikis, facilitating metastasis." (PMID 40694426, 2025). "Currently, clinical trials of DGAT1 and DGAT2 inhibitors for obesity, diabetes, and other metabolic disorders are being tested as a single agent or in combination with another metabolic regulatory drugs, such as acetyl-CoA carboxylase inhibitors." (PMID 38500157, 2024). "The expression of diacylglycerol O-acyltransferase 2 (Dgat2), responsible for triacylglycerol synthesis, and insulin-induced gene 2 protein (Insig2), involved in cholesterol synthesis and obesity, were down-regulated in FL." (PMID 38188177, 2024). "A high-fat diet significantly increased the relative expression of DGAT2 in the backfat and liver tissues and induced obesity in genetically lean pigs." (PMID 36643642, 2023). "Here we demonstrate that TRF upregulates genes involved in glycine production (Sardh and CG5955) and utilization (Gnmt), while Dgat2, involved in triglyceride synthesis is downregulated in Drosophila models of diet- and genetic-induced obesity." (PMID 36810287, 2023). "In our ongoing study, TRF intervention across HFD and genetically induced obesity resulted in the downregulation of diacylglycerol O-acyltransferase 2 (Dgat2) in muscle." (PMID 36613864, 2022). "The authors do not find (i) an association between variants or haplotypes and the genomic region of DGAT2, and (ii) an important role of common genetic variation in DGAT2 for the development of obesity." (PMID 33584351, 2021). "Suppression of Dgat2 is protective against excessive fat accumulation, obesity, and improved insulin resistance." (PMID 33946320, 2021). "The DGAT2 gene is located on chromosome 11q13 and, as a key enzyme in fat metabolism, is a candidate obesity gene." (PMID 30328513, 2019).
Obesity (continued). "Despite a number of previous studies on the DGAT1 and DGAT2 genes, which have emphasized their importance as potential obesity treatment targets to increase triacylglycerol accumulation, little is known about their evolutionary timeline in eukaryotes." (PMID 21933415, 2011). "DGAT2 is a promising candidate gene for obesity because of its function as a key enzyme in fat metabolism and because of its localization on chromosome 11q13, a linkage region for extreme early onset obesity detected in our sample." (PMID 17477860, 2007). "Importantly, the concurrent upregulation of Fasn and Dgat2 in gonadal adipose is consistent with the obesity phenotype observed in Glo1+/− mice." (PMID 39896461, 2025). "We first observed that DGAT2 is highly expressed in the adipose tissue when compared to the liver, with significantly higher adipose expression (p-value = 4.23 × 10−4 by the Wilcoxon rank sum test) in the females (n = 182) than males (n = 80) with obesity." (PMID 38991381, 2024). "Recently, a positive correlation of DGAT2 genes with obesity has been reported." (PMID 36290086, 2022). "CCDC80 is a secreted protein that regulates adipocyte differentiation, whereas DGAT2 is an enzyme that catalyzes the final step of mammalian triglyceride synthesis and may be involved in the mechanisms of obesity, insulin resistance, and leptin resistance." (PMID 23741331, 2013). "In conclusion, our results do not support the hypothesis of an important role of common genetic variation in DGAT2 for the development of obesity in our sample." (PMID 17477860, 2007). "In light of the small sample size, which leads to considerable stochastic variation in the location estimate of linkage peaks and combined with its important role in fat metabolism DGAT2 is a very plausible positional and functional candidate gene for obesity in our sample." (PMID 17477860, 2007). "Reduced DGAT2 expression could be partially due to a feedback mechanism involving excessive lipid accumulation in the liver, which has been observed in a mouse model of high-fat diet-induced obesity." (PMID 26114429, 2015). "From our transcriptomic data, the expression levels of Dgat2/CG1942 were downregulated under TRF in WT and obesity models." (PMID 36810287, 2023). "Diacylglycerol O-Acyltransferase 2 (DGAT2) is a critical catalysing enzyme for triglyceride (TG) biosynthesis and storing fat, resulting in obesity in humans." (PMID 36290086, 2022). "However, in the 262 individuals with obesity from the KOBS cohort, we observed a 166-fold higher expression of DGAT2 in their adipose tissue than in their liver." (PMID 38991381, 2024). "However, high-fat diet intake did not alter the relative gene expression of Dgat2, which could contribute to maintaining DGAT2 protein availability for TAG synthesis and lead to lipid droplet expansion during obesity." (PMID 39859293, 2025). "Although both DGAT1 and DGAT2 catalyze the same reaction in the last step of triglyceride synthesis, often in the same cells, DGAT1 but not DGAT2 has been pursued for more than a decade as a therapeutic target for obesity and metabolic disorders such as insulin resistance." (PMID 31345219, 2019).
Insulin resistance (25 papers, 2008 to 2025). Increased resistance towards insulin, that is, diminished effectiveness of insulin in reducing blood glucose levels. "Deletion or knockdown of either DGAT1 or DGAT2 provokes DG accumulation at the ER, which has been tightly linked to lipotoxicity, ER stress, and the development of insulin resistance." (PMID 33872605, 2021). "Interestingly, Dgat2 is also implicated in having a direct role in insulin resistance." (PMID 36613864, 2022). "Another study that utilized an antisense oligonucleotide against Dgat2 also showed that knocking down Dgat2 protected against fat-induced hepatic insulin resistance due to decreased DAG amount and protein kinase C epsilon activation." (PMID 37644753, 2023). "A recent study found that overexpression of Dgat2 in glycolytic type 2 muscle led to increased lipid accumulation and insulin resistance in mice." (PMID 36810287, 2023). "An early study reported that Tangduqing granules decrease DGAT2 expression, resulting in a relief of insulin resistance and hypertriglyceridemia in a T2DM rat model." (PMID 36438823, 2022). "The downregulation of Dgat2 under TRF suggests a possible mechanism in which TRF mediates insulin resistance under HFD." (PMID 36613864, 2022). "Another significant gene from the transcriptomic profiling, diacylglycerol O-acyltransferase 2 (DGAT2), is involved in the production and accumulation of triglycerides in tissues and has been linked with insulin resistance and diabetes." (PMID 32848883, 2020). "In humans, the DGAT2 gene was reported to be a candidate for the dissociation between fatty liver and insulin resistance, and this result has also been observed in mice." (PMID 28340555, 2017). "Variations in the adiponectin receptor 1 (ADIPOR1) and diacylglycerol O-acyltransferase 2 (DGAT2) genes have been reported to be associated with fatty liver and insulin resistance in the Caucasian population." (PMID 21176169, 2010). "Interestingly, a recent study demonstrated that pharmacological inhibition of DGAT2 and consequently DG accumulation provokes hepatic insulin resistance in mice." (PMID 33872605, 2021). "For instance, hepatic overexpression of DGAT2, or liver-specific deletion of Histone deacetylase 3 (Hdac3), causes severe TG accumulation in liver, but does not promote insulin resistance in mice." (PMID 32170127, 2020). "In summary, the present study demonstrated that the widely used traditional Chinese medicinal formula “Tangduqing granules” was capable of reversing insulin resistance and lipid metabolism disorder in diabetic rats, at least partly through coordinated regulation of PPARγ and DGAT2 signal molecules." (PMID 31019978, 2019). "Analysis of the role of human genetic variability in lifestyle intervention has shown that the DGAT2 gene polymorphism is related to a decrease in liver fat, while changes in insulin resistance are not correlated." (PMID 24786095, 2014). "Human genetic variability analysis of a lifestyle intervention has shown that the DGAT2 gene polymorphism is related to a decrease in liver fat, while changes in insulin resistance do not correlate." (PMID 24132155, 2013). "It has been reported that Dgat2 is regulated by Leptin and is involved in insulin resistance." (PMID 18522719, 2008). "DGAT2 overexpression in the liver of mice increases hepatic TG content, leading to NAFLD and hepatic insulin resistance." (PMID 36438823, 2022). "Taken into conjunction with the downregulation of Dgat2, AdSL may also aid in TRF’s ability to combat insulin resistance under HFD conditions." (PMID 36810287, 2023). "Moreover, hepatic DGAT2 merits further attention as a parallel, or possibly alternative, drug target to DGAT1 for improving insulin resistance and reducing body weight." (PMID 31345219, 2019).
Insulin resistance (continued). "Moreover, DGAT2 could not compensate for the loss of DGAT1 in adipose tissue, demonstrated by the fact that DGAT1, but not DGAT2 deletion in combination with a HFD leads to ER stress, lipotoxicity, and systemic physiological changes such as insulin resistance." (PMID 40083687, 2025).
steatosis (24 papers, 2016 to 2025). Increased lipid within the cytoplasm of cells. "Furthermore, DGAT2 itself can promote the association of mitochondria to the ER, and DGAT2 deletion decreases steatosis and hypertriglyceridemia." (PMID 33276146, 2021). "DGAT2 inhibition successfully increased liver FFA level more than two‐fold and liver steatosis was extensively reduced in the DGAT2 ASO‐treated group." (PMID 38874196, 2025). "We found significantly higher DGAT2 expression in the adipose RNA-seq for all three liver phenotypes when compared to the controls (p-value = 0.0039, 0.0051, 0.013 for steatosis, fibrosis, and MASH, respectively)." (PMID 38991381, 2024). "Next, we compared the expression of DGAT2 between individuals diagnosed with steatosis (n = 154), fibrosis (n = 115), or NASH (n = 81) vs the controls (n = 86 for all tests)." (PMID 38991381, 2024). "Their hits elucidated the cyclin D3-cyclin-dependent kinase 2–4 (CDK2-4)/CCAAT-enhancer-binding proteins (C/EBP)/diacylglycerol acyltransferase 2 (DGAT2) pathway as contributing to endoplasmic reticulum stress-induced steatosis." (PMID 39000384, 2024). "Nile Red staining and quantitative assessments corroborated the strong reduction in the steatosis level upon DGAT2 KO, reverting to WT organoid levels." (PMID 36823355, 2023). "Combined DGAT1 and DGAT2 inhibition provided a synergistic effect that completely reverted the steatosis phenotypes of both genetic and FFA-induced steatosis models, already evident at nanomolar concentrations." (PMID 36823355, 2023). "A possible future strategy for NASH therapeutics may be to combine the depletion of MCT1 in stellate cells to decrease fibrosis with a potent anti-steatosis target such as DGAT2 which we and others have shown is effective in reducing steatosis when depleted." (PMID 38564479, 2024). "Inhibition of ACC, FAS or DGAT2 posed obvious steatosis-reducing effects." (PMID 36823355, 2023). "Furthermore, diacylglycerol o-acyltransferase 2 (DGAT2) and not PLIN5 appears to be the mediator in mitochondria segregation and ER-anchored lipogenic mitochondria generation, as demonstrated by the reduction on steatosis and hypertriglyceridemia upon DGAT2 ablation." (PMID 37106795, 2023). "Expression of hepatic genes related to lipid metabolism (Cpt1a, Atgl, Mgl, Dgat2, Srebp, Plin2) and OS (catalase, Edem) were modulated by FB23, although hepatic steatosis remained unchanged." (PMID 39984825, 2025). "Inhibition of diacylglycerol O-acyltransferase 2 (DGAT2), which catalyzes the final reaction of TAG synthesis, also strongly reduced steatosis in all models." (PMID 36823355, 2023). "To summarize, our results indicate that in steatosis the hepatic expression of DGAT-1, DGAT-2, FASN, and SREBP-1 increased significantly, and this increase was counteracted by the treatment with the nutraceutical formulation." (PMID 36135761, 2022). "However, in alternative animal models (such as those using diets high in fructose, saturated fat, and cholesterol 159, or Western diets 160), DGAT2 inhibition reduced steatosis without affecting inflammation or fibrosis in the latter." (PMID 39897559, 2025). "Using steatosis score as the readout, they scanned a panel of anti-NAFLD drugs (positive on animal models), and found inhibitors of ACC, FAS and DGAT2, a FXR agonist, as well as recombinant hFGF19 could efficiently alleviate the steatosis in FFA models and APOB−/−or MTTP−/− models." (PMID 37009924, 2023).